CRP (C-reactive protein)
Diseases named in the same sentence as CRP in open-access papers (continued):
Sharing a sentence is not in itself a finding about the gene and the disease.
acute respiratory distress syndrome (107 papers, 2009 to 2025). Progressive and life-threatening pulmonary distress in the absence of an underlying pulmonary condition, usually following major trauma or surgery. "SARS-CoV-2 with acute respiratory distress syndrome (ARDS) during the early phase of the recent pandemic caused a surprisingly high rise of CRP levels indeed." (PMID 39211771, 2024). "This is consistent with studies that have shown elevated CRP levels to be associated with severe disease, including complications such as acute respiratory distress syndrome (ARDS) and myocardial injury, in psychiatric patients." (PMID 39408010, 2024). "The infection triggers the excessive production of pro-inflammatory cytokines (such as IL-6, TNF-a, IL-1, and CRP), thereby inducing acute respiratory distress syndrome." (PMID 40260091, 2025). "Among the patients who died, significant risk factors were older age, comorbidities, low oxygen tension, high CRP, low lymphocytes, and complications such as acute cardiac injury, acute respiratory distress syndrome, shock, and DIC." (PMID 39618677, 2024). "Increased CRP, a significant indicator of poor prognosis in acute respiratory distress syndrome, suggests a chronic inflammatory state." (PMID 37362565, 2023). "Specifically, elevated CRP is an important sign of the poor prognosis of acute respiratory distress syndrome, reflecting the persistent state of inflammation." (PMID 35509104, 2022). "Furthermore, elevated serum CRP levels have been repeatedly associated with the onset of cardiovascular events, the development of acute respiratory distress syndrome (ARDS), and mortality due to infection by SARS-CoV-2." (PMID 35456328, 2022). "The variables mainly related to mortality were acute respiratory distress syndrome, mechanical ventilation, ICU stay, and higher C reactive protein measurements in patients with PE associated with severe COCID-19 patients." (PMID 34911551, 2021). "The second potential adverse outcome is hyperinflammation, characterized by high levels of C-reactive protein (CRP), interleukin (IL)-6, and tumor necrosis factor alpha (TNF-α), which can increase the risk of PLWH developing acute respiratory distress syndrome (ARDS)." (PMID 39597537, 2024). "CRP has been used as a prognostic variable in acute respiratory distress syndrome." (PMID 37362407, 2023). "CRS is an acute inflammatory syndrome characterized by fever and multi-organ dysfunction associated with raised inflammatory markers including C-reactive proteins (CRP) and Interleukin-6 (IL-6) which can result in acute lung injury and acute respiratory distress syndrome (ARDS)." (PMID 34650867, 2021). "Moreover, a high concentration of CRP as an inflammatory indicator and poor immune function was associated with death and a high concentration of AST was a risk factor for acute respiratory distress syndrome in these patients." (PMID 33468081, 2021). "In COVID-19, RVLS inversely associates with myocardial injury, mechanical ventilation, acute respiratory distress syndrome (ARDS), and mortality, as well as signs of systemic inflammation such as heart rate, D-dimer, and C-reactive protein, as well as thromboembolism." (PMID 33344513, 2020). "The finding that the serum CRP level is a predictor of AE-IP suggests that acute respiratory distress syndrome (ARDS) may have been triggered by infection in our patients who underwent non-pulmonary surgery." (PMID 31307466, 2019). "Thus, the potential association between high CRP and mortality would be explained, at least in part, by the presence of hyperinflammation, leading to severe complications like acute respiratory distress syndrome (ARDS), cardiovascular disease, and multiple organ failure." (PMID 39685758, 2024). "The patient was diagnosed with acute respiratory distress syndrome (ARDS) due to sepsis because of significant inflammatory findings, including a white blood cell count of 1200/μL and a C-reactive protein level of 17.1 mg/dL." (PMID 36894896, 2023).
acute respiratory distress syndrome (continued). "For example, TNF-α upregulates the expression of TF in acute respiratory distress syndrome (ARDS), and CRP drastically increases TF expression." (PMID 26667361, 2016). "ARDS: acute respiratory distress syndrome; CRP: C-reactive protein." (PMID 38533136, 2024). "Additionally, subjects with COVID-19 and acute respiratory distress syndrome (ARDS) have classical serum biomarkers of cytokine release syndrome, including elevated C-reactive protein lactate dehydrogenase D-dimer and ferritin levels." (PMID 37324739, 2023). "Higher serum levels of Gal-3 were related to a tendency of severe acute respiratory distress syndrome (ARDS) development, and alongside IL-6 and CRP, Gal-3 was demonstrated to be the best predictive power for mortality outcome." (PMID 35204790, 2022). "Among inflammatory biomarkers, CRP, Ferritin, and LDH are some of the main biomarkers responsible for the hyperinflammatory response, which leads to acute respiratory distress syndrome and multiple organ failure." (PMID 35054342, 2022). "O2, Oxygen; SaO2, oxygen saturation; CRP, C-reactive protein; FEU, fibrinogen equivalent units; NLR, neutrophil-lymphocyte ratio; ARDS, acute respiratory distress syndrome." (PMID 34055545, 2021). "We studied the value of routine biochemical variables albumin, C-reactive protein (CRP) and lactate dehydrogenase (LDH) to improve prediction and monitoring of acute respiratory distress syndrome (ARDS) severity in the intensive care unit." (PMID 25888398, 2015). "Interestingly, PNN (polynuclear neutrophil) levels on day 5 proved to be a better predictor of intubation, acute respiratory distress syndrome (ARDS), and mortality than the initial PNN counts, C-reactive protein, or procalcitonin." (PMID 40002608, 2025). "It is expensive compared to CRP and WBC, and may falsely rise in cases of acute respiratory distress syndrome, chemical pneumonitis and severe falciparum malaria." (PMID 36167572, 2022). "Surrogate clinical (H-score, acute respiratory distress syndrome) and circulating biomarkers (Ferritin, CRP) were used as evidence for cytokine storm rather than a quantitative assessment of cytokines." (PMID 33921604, 2021). "In addition, we also found that other features such as Age at admission, PaO2/FiO2 (the ratio of arterial oxygen partial pressure (PaO2 in mmHg) to fractional inspired oxygen (FiO2)), TropT, Ferritin, ventilation, C-reactive protein (CRP), and Symptom of Acute respiratory distress syndrome (ARDS)." (PMID 39820088, 2025). "Acute respiratory distress syndrome (ARDS), lower arterial oxygen saturation, higher white blood cell (WBC) count, and higher C-reactive protein (CRP) were the main determinants of death." (PMID 38431948, 2023). "ARDS: acute respiratory distress syndrome; CPAP: continuous positive airway pressure; CRP: C-reactive protein; MPP: methylprednisolone pulse; TPE: therapeutic plasma exchange." (PMID 36407237, 2022). "PEVs that are HMGB1 positive are increased in COVID-19 and correlate positively with CRP levels, LDH expression, d-dimer, acute respiratory distress syndrome (ARDS), and patient WHO score." (PMID 35887184, 2022). "An immunomodulant is administrated in the presence of ARDS (Acute Respiratory Distress Syndrome), or progressive worsening of respiratory activity and MIS (Multisystem Inflammatory Syndrome), an increase of IL-6 and/or D-dimer and/or ferritin and/or C-reactive protein." (PMID 34576859, 2021). "We used only regular blood tests with complete white blood cell count, serum electrolytes and CRP, and did not evaluate LDH or D-dimers, since they seem to be mainly correlated with severity and have been described as risk factors for acute respiratory distress syndrome." (PMID 33332360, 2020).
acute respiratory distress syndrome (continued). "For inflammatory biomarkers, the elevated levels of CRP, D-dimer, and ferritin in ICU patients support the ‘cytokine storm’ theory, describing an excessive inflammatory response that can lead to acute respiratory distress syndrome (ARDS) and multi-organ failure." (PMID 40860652, 2025). "He had a normal chest X-ray (CXR) and normal blood samples except for minor C-reactive protein (CRP) elevation (11 mg/L) only 43 h before he was admitted directly to the intensive care unit (ICU) with septic shock and acute respiratory distress syndrome (ARDS)." (PMID 35076575, 2021).
renal dysfunction (105 papers, 2006 to 2025). "Negative trends are especially apparent with uric acid, serum creatinine, urea, and CRP, suggesting that higher levels of these markers-often associated with inflammation or renal dysfunction-correspond with lower vitamin D status." (PMID 40265109, 2025). "In our study, patients experiencing an infectious episode had more comorbidities (a higher CCI) and higher CRP, both of which can result in a higher risk of renal dysfunction." (PMID 36079917, 2022). "In our study, severe initial renal dysfunction (eGFR < 30 ml/min) was associated with significant elevation of systemic inflammatory markers, such as CRP and white blood cell count." (PMID 34485326, 2021). "As the relationship between renal markers and total burden of cSVD remained same after adjustment for CRP, it is unlikely that underlying inflammation is the only explanations for the association between renal dysfunction and cSVD in the present observation." (PMID 29930507, 2018). "We also found that CRP increased with increasing renal dysfunction and that its levels were associated with the extent of CAD, suggesting that this proteinas inflammation mediator represents a link between renal dysfunction and CAD." (PMID 25230678, 2014). "In pre-dialysis CKD patients, plasma homoarginine concentration is associated with the severity of renal dysfunction as well as with biomarkers of protein energy wasting and inflammation (body mass index, serum albumin and C-reactive protein)." (PMID 24023762, 2013). "Another debate concerns whether cumulative exposure to CRP predisposes to aggravation of renal dysfunction." (PMID 37974082, 2023). "However, the intraoperative lactate level, perioperative renal dysfunction (defined by elevated creatinine) and the grade of inflammation (defined as elevated CRP values) were factors associated with hemodynamic instability." (PMID 36615185, 2023). "In addition, CRP was pinpointed to exacerbate renal dysfunction among smokers, who are at peculiar risk of developing CAD." (PMID 37974082, 2023). "Patients with comorbidities, lower lymphocyte counts in hemogram, platelet count and serum albumin, high C-reactive protein level, and renal dysfunction may have higher risk for death." (PMID 33762058, 2022). "However, the development of an elevated WCC, CRP, and renal dysfunction during admission was significantly associated with 3-month mortality." (PMID 31446184, 2020). "When the relationships between inflammatory markers and renal dysfunction (as a continuous variable) were analyzed using multiple linear regression and adjusted for comorbidities, age, and gender, CRP and UA remained significantly associated with the degree of renal dysfunction." (PMID 25230678, 2014). "Inflammatory markers such as C-reactive protein have been shown to predict prognosis both in cardiac and renal dysfunction independently from traditional cardiovascular risk factors, and although it is linked to prognosis in HFpEF, this association might be comorbidity driven." (PMID 36158149, 2022). "The inflammatory marker high-sensitivity C-reactive protein (hs-CRP) was significantly lower in the High-GFR group, and individuals with elevated hs-CRP (>0.5 mg/dL) had a 1.71-fold higher risk of renal dysfunction." (PMID 40077791, 2025). "CRP levels were also higher in obese patients with AKI (62 ± 14 mg/L), showing a significant association with renal dysfunction (OR: 1.09 per 10 mg/L increase, 95% CI: 1.04–1.14, p = 0.002)." (PMID 40002762, 2025). "Consistent with this, significantly elevated ESR and CRP levels were observed in CKD patients, likely reflecting the chronic inflammatory state associated with renal dysfunction." (PMID 40358366, 2025). "For laboratory markers, moderate-to high-specificity was observed for markers of inflammation (detectable CRP; specificity 77.9%), nutritional or inflammatory status (low albumin; specificity 72.2%), and renal dysfunction (reduced eGFR; specificity 86.4%)." (PMID 40804822, 2025).
renal dysfunction (continued). "By multivariate analysis, renal dysfunction at diagnosis and elevated CRP levels were independent predictors of 30-day mortality." (PMID 30717116, 2019). "Laboratory findings showed proteinuria (1.57 g/g・creatinine using spot urine), renal dysfunction (serum creatinine 1.08 mg/dL), and higher CRP level (16.7 mg/dL)." (PMID 31623576, 2019). "Low magnesium was significantly and strongly associated with increased BMI, heavy drinking, AF, renal dysfunction, use of antihypertensive drugs, HOMA-IR, CRP, IL-6, vWF, cTnT and NT-proBNP." (PMID 29663176, 2018). "Previous studies also reported that circulating levels of CRP in elderly subjects were positively correlated with levels of blood glucose and HbA1c, but inversely correlated with renal dysfunction." (PMID 30202420, 2018). "When stratified by eGFR and CFR, in women with renal dysfunction, CRP, IL-6, and SAA were higher in those with low CFR compared with those with normal CFR." (PMID 25951606, 2015). "CRP was positively correlated with renal dysfunction and the number of involved coronary vessels, confirming its potential as a biomarker." (PMID 25230678, 2014). "CRP was also positively correlated with renal dysfunction, confirming its possible use as a biomarker of the extent of coronary atherosclerosis in patients with CKD." (PMID 25230678, 2014). "Similar results were shown in the Cardiovascular Health Study, which demonstrated cystatin C was correlated with CRP and fibrinogen in patients with mild to moderate renal dysfunction." (PMID 22978689, 2012). "Renal damage in patients with significant GFR impairment may have increased acute-phase reactant CRP independently of infection, while decreased procalcitonin clearance due to renal dysfunction may have contributed to elevated levels." (PMID 40528397, 2025). "When patients present with unexplained flu-like illnesses, chest radiography, testing to detect hepatic dysfunction, renal dysfunction, or elevated CRP and procalcitonin levels, and obtaining an exposure history (including contact with parrots, goats, or poultry) are essential." (PMID 41465955, 2025). "However, CRP was more elevated in patients with severe renal dysfunction (eGFR <30 mL/min) (CRP: 132.7 ± 18.47 mg/L) that in patients in the other two groups." (PMID 34485326, 2021). "Interestingly, for the choroid, there were strong correlations between its thickness and the level of systemic inflammation (measured using high-sensitivity CRP [hsCRP]) and degree of renal dysfunction (represented by eGFR and proteinuria)." (PMID 27942587, 2016). "CRP and uric acid (UA) were significantly higher in patients with severe renal dysfunction." (PMID 25230678, 2014). "Although increased inflammation in renal dysfunction could be a possible underlying mechanism, the association between CRP level and presence of CMB was not significant in this study (observed using a dummy variable of CRP level with various cutoffs)." (PMID 28207801, 2017). "TMAO positively correlated with renal dysfunction and inflammation markers such as log-BUN (r = 0.340, p < 0.001), log-creatinine (r = 0.282, p = 0.002), log-UACR (r = 0.326, p < 0.001), and log-CRP (r = 0.373, p < 0.001)." (PMID 41470244, 2025). "CRP levels, BUN, renal dysfunction, respiratory dysfunction and antibiotic use were significantly associated with mortality." (PMID 40699042, 2025). "We also found that higher levels of GAS6 and clinical biomarkers, including NT-proBNP, TnT, BUN and CRP, were accompanied by highest mortality in AHF patients, especially in those with renal dysfunction." (PMID 36635690, 2023). "While GP73 levels did not correlate with serum markers of liver (AST, bilirubin, ALP and GGT) or renal dysfunction (creatinine), we observed a significant positive correlation between GP73 and CRP serum levels (rS:0.393, p < 0.001)." (PMID 36139589, 2022).
renal dysfunction (continued). "Participants with renal dysfunction at baseline were older and showed significantly higher values of PP, fasting glucose, insulin, HOMA, UA and hs-CRP, and lower values of HDL-cholesterol and pre-bronchodilator FEV1." (PMID 34444971, 2021). "By univariate Cox analysis, age, active malignancy, systolic blood pressure, renal dysfunction at diagnosis, BNP and CRP level were significant predictors of 30-day mortality." (PMID 30717116, 2019). "C-reactive protein (CRP) and uric acid levels were significantly increased in patients with severe renal dysfunction (SRD) by bivariate and multivariate analyses, adjusted for gender, age and comorbidities at admission." (PMID 25230678, 2014). "Although baseline characteristics were similar, non-survivors had higher white cell counts and levels of C-reactive protein and renal dysfunction." (PMID 31446184, 2020). "However, our inclusion criteria allowed patients with chronic diseases, which can directly affect the CRP and PCT levels (such as malignancy and renal dysfunction)." (PMID 33365277, 2020). "Recent data support the concept that C-reactive protein (CRP) is associated with the prevalence, progression and prognosis of renal dysfunction in non-Hispanic whites." (PMID 20078870, 2010). "Notably, patients with renal dysfunction had significantly higher median CRP levels on admission than those without renal dysfunction (13.5 mg/dL vs. 1.2 mg/dL, p < 0.001)." (PMID 40046517, 2025).